IL10RA (interleukin 10 receptor subunit alpha)
Diseases named in the same sentence as IL10RA in open-access papers (continued):
Sharing a sentence is not in itself a finding about the gene and the disease.
cancer (30 papers, 2014 to 2025). A tumor composed of atypical neoplastic, often pleomorphic cells that invade other tissues. "The network surrounding Il10ra shows that many of them are cancer related, e.g., Reg3g, Aoc1, Mep1a, Irf7, Gas6, B3gnt7, Tap1, Tgm2, and Nos2." (PMID 33396408, 2020). "In the network surrounding Il10ra, many of the downstream differentially expressed genes are cancer related." (PMID 33396408, 2020). "Some of the significant cancer hallmark terms are inflammatory response (CD14, CD69, IL10RA), KRAS signaling up (CD37, IL10RA, GPNMB), IL-6/JAK/STAT3 signaling (CD14, CSF2RB), Interferon Gamma Response (CD69, CSF2RB, IL10RA, VCAM1, SLAMF7), TNF-alpha Signaling via NF-kB (CD69)." (PMID 35486660, 2022). "They claimed that IL10RA regulates immune system response in cancer environments." (PMID 35486660, 2022). "In contrast the expression of MT1X, MT2A, IL10RA, KIT was lower in cancer tissues as compared to normal tissues." (PMID 33240582, 2020).
infectious disease (3 papers, 2016 to 2023). A disorder directly resulting from the presence and activity of a microbial, viral, or parasitic agent in humans. "The enrichment of pathogenic IL10RA variants across East Asia and characteristic endemic presence of infectious disease with known functional link to the IL-10 signaling pathway led us to hypothesize that these variants mediate environment-specific increased fitness in heterozygous carriers." (PMID 36370291, 2023). "Although our data strongly suggest that the accumulation of multiple pathogenic IL10RA variants in East Asia is not a chance finding, we cannot definitively link those genetic variants to one single infectious disorder." (PMID 36370291, 2023).
kidney disease (2 papers, 2021 to 2022). "Our findings indicate that a high expression of different co-DEGs was correlated with a low glomerular filtration rate in kidney disease samples (IL10RA, HLA-DPA1, r = −0.490, p < 0.001; IRF8, HLA-DRA, r = −0.500, p < 0.001; HLA-DPB1, r = −0.510, p < 0.001; HLA-DMA, r = −0.480, p < 0.001)." (PMID 34692653, 2021).
lung (2 papers, 2011 to 2025). "To determine if the effector T cell-derived IL-10 had any impact on the outcome of RSV infection, we examined the effect of blockade of the IL-10 receptor (IL-10R) by in vivo administration of a blocking anti-IL-10Rα (α-IL-10R) mAb on virus clearance, pulmonary function and lung inflammation." (PMID 21829368, 2011).
genetic disorder (1 paper, 2025). "IL10RA-deficient IBD, an autosomal recessive genetic disorder, has been documented to be inherited through the conventional compound heterozygous or homozygous mutation patterns from both parents." (PMID 40611267, 2025).
IL10RA also shares sentences with these, for which no sentence is quoted: parasitemia (12 papers); inflammation (6); ulcerative colitis (6); B cell lymphoma (5); chronic granulomatous disease (5); colon carcinoma (5); Granuloma (5); breast carcinoma (3); lupus (3); lymphopenia (3); psoriasis (3); virus infection (3); acute myeloid leukemia (2); anaemia (2); asthma (2); autoimmune disease (2); bladder cancer (2); cardiac hypertrophy (2); common variable immunodeficiency (2); diabetes (2); enteritis (2); Failure to thrive (2); helminthiasis (2); hematologic disorder (2); Hepatic fibrosis (2); Hypertension (2); influenza (2); leishmaniasis (2); leprosy (2); nasal polyps (2).
A further 115 diseases each share a sentence with IL10RA in 2 papers or fewer.